RET (ret proto-oncogene)
Diseases named in the same sentence as RET in open-access papers (continued):
Sharing a sentence is not in itself a finding about the gene and the disease.
retinoblastoma (2 papers, 2011 to 2016). A malignant tumor that originates in the nuclear layer of the retina.
sarcomatoid carcinoma (2 papers, 2015 to 2024). A malignant epithelial neoplasm characterized by the presence of spindle cells and anaplastic morphologic features. "Eight sarcomatoid carcinoma were analyzed for the presence of EGFR kinase domain mutations, KRAS mutations, HER2 kinase domain mutations, BRAF mutations, ALK fusions, RET fusions and AKT1 mutations." (PMID 26486077, 2015).
schizophrenia (2 papers, 2012 to 2022). A major psychotic disorder characterized by abnormalities in the perception or expression of reality. "In addition to the pleiotropic effect of neuregulins and ErbB families, the major HSCR gene, RET, was found deleted exclusively in schizophrenia patients in a recent genome-wide CNV analysis." (PMID 22589734, 2012). "In dopamine neurons, GDNF mainly signals via RET receptor, suggesting that RET inhibitors such as Selpercatinib and Pralsetinib, currently used in cancer therapy, may carry potential to treat a subgroup of patients with schizophrenia." (PMID 35618883, 2022).
Soft tissue tumors (2 papers, 2016 to 2026). "A meta-analysis of public expression array datasets from 434 human tumor samples, pointed out expression of RET as typically for MLS compared to other soft tissue tumors." (PMID 26595521, 2016).
T-cell acute lymphoblastic leukemia (2 papers, 2023 to 2024). Acute lymphoblastic leukemia of T-cell origin. "Notably, we have reaffirmed the well-established associations between transcription factors TLX1 and TLX3 with T-cell acute lymphoblastic leukemia, as well as HOXA11, PREX2, and RET with AML." (PMID 38769532, 2024).
thymoma (2 papers, 2022). A neoplasm arising from the epithelial cells of the thymus.
Thyroid adenoma (2 papers, 2021). The presence of a adenoma of the thyroid gland. "Activation of the RET gene by rearrangement (inversion or translocation) appears to be only seen in patients suffering from PTC or thyroid adenoma, and germline missense mutations of the RET gene have been shown to be the cause of the hereditary form of MTC (MEN2)." (PMID 34777782, 2021). "RET/PTC could also be found in benign thyroid lesions such as thyroid adenomas and Hashimoto thyroiditis." (PMID 34684168, 2021).
tumor syndromes (2 papers, 2012 to 2024). "Multiple endocrine neoplasia (MEN) syndromes are part of a spectrum of clinically well-defined tumor syndromes ultimately characterized by histologically similar tumors arising in patients and families with mutations in one of the following four genes: MEN1, RET, CDKN1B, and MAX." (PMID 39336996, 2024).
xerosis (2 papers, 2025). "For instance, VEGFR inhibition is strongly associated with hand-foot syndrome (HFS), xerosis, and nail disorders, while selective RET or NTRK inhibitors may cause rash, pruritus, or pigmentary changes—often with a milder overall profile but longer cumulative exposure." (PMID 41463055, 2025). "Xerosis is one of the most frequently encountered but often underappreciated dermatologic toxicities of TKIs, particularly those that interfere with epidermal signaling such as EGFR, RET, and MAPK-related pathways." (PMID 41463055, 2025).
adrenal cortical carcinoma (1 paper, 2018). "RET mutations in adrenal cortical carcinoma or NSCLC, using cabozantinib-s-malate, sorafenib tosylate, regorafenib or sunitinib malate." (PMID 29507702, 2018).
anaplastic ependymoma (1 paper, 2023). Anaplastic ependymoma is a rare, malignant type of ependymoma that most often arises in the supratentorial region of the brain of children and young adults and that manifests with variable symptoms including headaches, nausea, vision impairment, memory loss and difficulty walking. "Notably, synonymous variants found in this tumor were detected in other tumors, such as APC (rs41115) variant in MPE, FGFR3 (rs7688609), PDGFRA (rs1873778), and RET (rs1800861) in anaplastic ependymoma Grade III tumor, a-CPP, and myxo-papillary ependymoma (MPE) tumors." (PMID 37273678, 2023).
aplastic anemia (1 paper, 2024). Anemia resulting from bone marrow failure (aplastic or hypoplastic bone marrow). "Other studies noted that anti-M antibodies could result in aplastic anemia, with reduced RET counts indicating insufficient hematopoietic activity in these cases." (PMID 39767838, 2024).
Arrhythmia (1 paper, 2024). Any cardiac rhythm other than the normal sinus rhythm. "RET-inhibiting cancer drug regorafenib was found to induce cardiac ischemia, which would create a substrate for arrhythmia, thus increasing AF and HF risk." (PMID 39434187, 2024).
asthma (1 paper, 2026). "Here, we investigate the role of glial cell-line derived neurotrophic factor (GDNF) and rearranged during transfection (RET) signaling in PNEC hyperplasia and its therapeutic potential in asthma." (PMID 41968620, 2026).
biliary tract cancer (1 paper, 2022). "Authors concluded that RET fusion is a tumor-agnostic target for RET inhibitor and the latest NCCN guidelines now list pralsetinib as a treatment option for RET fusion-positive biliary tract cancer from the first-line setting." (PMID 36290850, 2022). "The prevalence of RET fusion is estimated to be extremely low in biliary tract cancer and no cases were identified in 1573 patients with biliary tract cancer registered in cBioPortal." (PMID 36290850, 2022).
bone cancer (1 paper, 2023). A primary or metastatic malignant neoplasm affecting the bone or articular cartilage. "In an animal model of bone cancer pain, RET can bind to the ligand GDNF to activate the downstream ERK signaling pathway, and promote sensitization of DRG neurons." (PMID 37250405, 2023).
carcinoid tumours (1 paper, 2020). "Radiological examinations such as MRI or CT are helpful to detect pituitary, pancreatic, adrenal or carcinoid tumours while DNA analysis helps ascertain germline mutations including MEN1, RET and CDKN1B." (PMID 31797261, 2020).
Cerebellar hypoplasia (1 paper, 2021). Cerebellar hypoplasia is a descriptive term implying a cerebellum with a reduced volume, but a normal shape and is stable over time. "Therefore, further studies are needed to investigate RET-mediated cerebellar hypoplasia in patients and to develop new therapeutic strategies targeting RET-related molecules against cerebellar hypoplasia." (PMID 33561442, 2021).
Chylothorax (1 paper, 2023). The presence of chyle in the thoracic cavity. "Chylous ascites and chylothorax may occur secondary to some multi-kinase and selective RET inhibitors." (PMID 38118420, 2023).
cocaine addiction (1 paper, 2023). "Here, through independent accumbal GDNF or VTA RET reduction after establishment of cocaine-induced conditioned place preference, we investigate this pathway’s potential to treat cocaine addiction." (PMID 37238631, 2023). "Taken together, our findings indicate that appropriate GDNF activity in NAc and dampened RET activity in the VTA facilitates recovery from cocaine addiction." (PMID 37238631, 2023). "We report that a 60–70% reduction of RET after the onset of cocaine addiction in the VTA hastens CPP extinction and reduces preference upon reinstatement compared to controls." (PMID 37238631, 2023). "Our results imply that, in theory, the application of RET blockers which preferentially block internalized RET signaling in the VTA cell bodies could serve as future treatment of cocaine addiction." (PMID 37238631, 2023). "Thus, RET antagonism in the VTA coupled with intact or enhanced accumbal GDNF function may provide a new approach towards cocaine addiction treatment." (PMID 37238631, 2023). "Thus, reducing GDNF in the NAc and RET levels in the VTA have opposing roles in cocaine addiction." (PMID 37238631, 2023). "Thus, partial inhibition of RET in the VTA may be beneficial in treating cocaine addiction." (PMID 37238631, 2023). "This suggests that increased GDNF-RET signaling in the VTA enhances and the reduction in VTA RET levels reduces cocaine addiction." (PMID 37238631, 2023). "This suggests a specific role of NAc GDNF and VTA RET signaling in cocaine addiction, but not cocaine-induced motor activity." (PMID 37238631, 2023).
cognitive decline (1 paper, 2024). "As far as we know, there have been no documented cases of cognitive decline resulting from RET inhibitors." (PMID 39372206, 2024).
craniopharyngioma (1 paper, 2020). A benign, partly cystic, epithelial tumor of the sellar region, presumably derived from Rathke pouch epithelium. "We know that RET and GFRα3 expression is lost in craniopharyngiomas, a pituitary benign neoplasia possibly derived of some stem cell population where β-catenin activation and nuclear localization, either through mutation or BRAF kinase activation, has been described." (PMID 33071961, 2020).
cyst (1 paper, 2016). A sac-like closed membranous structure that may be empty or contain fluid or amorphous material. "Thus Yap/Taz deletion from the UB epithelium leads to the opposite effect from loss of Nf2 and excess YAP, namely expanded expression of RET pathway/tip genes and cyst-like branching, that may represent unrestricted outward expansion of a tip fate." (PMID 27480037, 2016).
dengue (1 paper, 2024). "We observed that EPHB3, ERBB2, FGFR2, IGF1R, and RET are upstream regulators both of kinases shown to be important in previous dengue research and of kinases predicted by KiR." (PMID 38585651, 2024).
diabetic retinopathy (1 paper, 2025). "Targeting RET with a small ligand, protein, or peptide hinders diabetic retinopathy progression." (PMID 40533788, 2025).
ependymoma (1 paper, 2025). A WHO grade II, slow growing tumor of children and young adults, usually located intraventricularly. "Nonetheless, the role of protein kinase signaling has been implied in ependymoma tumorigenesis, prompting several ongoing studies evaluating TKIs targeting RET, ALK, ROS, IGFR, PDGFR, FGFR, or EGFR, as well as inhibitors targeting PI3K, mTOR, KIT, and CDK4." (PMID 40238025, 2025).
epithelial ovary cancer (1 paper, 2020). "Endogenous RET is expressed in epithelial ovary cancer at both RNA and protein levels." (PMID 32293499, 2020).
erectile dysfunction (1 paper, 2023). Persistent or recurrent inability to achieve or to maintain an erection during sexual activity. "Erectile dysfunction (ED) has been reported clinically in patients on selective RET inhibitors, according to our institutional experience." (PMID 38118420, 2023).
eye tumors (1 paper, 2015). "Notably, among the tumors derived from RET mice the eye tumors exhibited the highest levels of VEGF-A expression." (PMID 26575174, 2015). "Interestingly, we showed previously in the same RET mouse model that surgical removal of eye tumors resulted in increased local and distant tumor growth and such growth was associated with increased TAM density." (PMID 26575174, 2015).
familial disease (1 paper, 2025). "Females had a higher prevalence of familial disease (28.2% vs. 8.2%; p < 0.01) and RET gene mutations (15.4% vs. 2.5%; p = 0.02)." (PMID 41042336, 2025). "Similar to results of previous studies an overall male–female ratio of 4:1 was observed, with a decreased sex-ratio in familial disease 1:0.9, RET-mutations 1:1.5, TCA 1:0.8, and syndromic HSCR 2.3:1." (PMID 41042336, 2025). "Females had a higher reported prevalence of familial disease (28.2% vs. 8.2%; p = 0.002) and a higher proportion of verified RET-mutations (15.4% vs. 2.5%; p = 0.019)." (PMID 41042336, 2025).
gastric tumors (1 paper, 2021). "However neither GRFAL expression nor especially the joint expression of GDF15, GFRAL and RET have been evaluated in gastric tumors, in the context of the potential implication of the body-weight signaling pathway in GC pathogenesis." (PMID 34149933, 2021).
goiter (1 paper, 2018). Enlargement of the thyroid gland usually caused by lack of iodine in the diet, hyperthyroidism, or thyroid nodules. "In the time-window of 10–17 months of age, thyroid carcinomas were present in 100% of RET/PTC1TG;Patz1−/−, whereas they were diagnosed in 54% and 58% of RET/PTC1TG;Patz1+/+ and RET/PTC1;Patz1+/− mice, respectively, that also show the presence of hyperplasia/goiter." (PMID 29584698, 2018).
hairy cell leukemia (1 paper, 2017). Hairy cell leukemia (HCL) is a rare type of leukemia in which abnormal B-lymphocytes are present in the bone marrow, spleen and peripheral blood. "RET p.G423R mutation has been reported in hairy cell leukemias." (PMID 28179590, 2017).
Hydroureter (1 paper, 2010). The distention of the ureter with urine. "However, in the absence of SPRY1, mice lacking GDNF or RET make a normal UB that develops into a normal ureter connected to the bladder, as indicated by the absence of hydroureter." (PMID 20084103, 2010).
hypercortisolism (1 paper, 2025). "Early identification of RET mutation types, precise management of hypercortisolism, and eradication of the primary tumor are essential to prevent complications and improve prognosis." (PMID 41306433, 2025). "After extensive surgery to remove MTC and BLA, along with a trial of a highly selective RET inhibitor, his hypercortisolemia was rapidly resolved." (PMID 41306433, 2025).
Hyperglycemia (1 paper, 2013). An increased concentration of glucose in the blood. "A previous study demonstrated that glucose concentration-dependent expression of GDNF and RET in human PC cells correlates with alterations of cell proliferation, suggesting GDNF and RET as hyperglycemia underlying mechanism inducing PC progression." (PMID 24303367, 2013).
hypersensitivity (1 paper, 2022). An inflammatory response to an exogenous environmental antigen or an endogenous antigen initiated by the adaptive immune system. "RET-inhibitors are effective regardless of previous treatment (including platinum-based chemotherapy with or without immunotherapy and untreated patients); the incidence of treatment-related hypersensitivity reactions may be higher in patients after immunotherapy." (PMID 35329956, 2022).
hypersensitivity reaction (1 paper, 2023). "In case of recurrence of the hypersensitivity reaction, it is recommended to permanently discontinue the RET inhibitor." (PMID 38118420, 2023).
hypoparathyroidism (1 paper, 2018). Hypoparathyroidism is an endocrine disorder in which the parathyroid glands in the neck do not produce enough parathyroid hormone (PTH). "Comparison of mutation-carrier relatives diagnosed with MTC after RET screening to index patients showed that those relatives had a lower frequency of complications, such as post-surgical hypoparathyroidism, and lower levels of sCt upon their last visit (p < 0.05)." (PMID 30624503, 2018). "An interesting finding was that relatives whose diagnoses of MTC/CCH were made after RET screening had lower sCt levels and less frequent postsurgical hypoparathyroidism than index patients and mutation-carrier relatives whose diagnoses of MTC/CCH were made before RET screening (p < 0.05)." (PMID 30624503, 2018).
intestinal atresia (1 paper, 2025). A congenital malformation characterized by the absence of a normal opening in a part of the intestine. "While most MEN2A patients have been reported to have no intestinal atresia, 2.5-5% of HD patients have RET variants, which could have a significant impact on the care of relatives." (PMID 40656247, 2025).
keratoacanthoma (1 paper, 2021). A dome-shaped, rapidly growing skin lesion composed of well differentiated squamous cells. "Keratoacanthomas have been previously reported in association with sorafenib treatment with possible involvement of RET proto-oncogene, PDGFR, and RAS pathway inhibition leading to epithelial proliferation with reduced antitumor immunity." (PMID 34544494, 2021).
kidney (1 paper, 2022). "Three novel missense variants which were absent in Gnomad were identified in PAX2 (p.Ser305Leu in child with unilateral hypodysplastic kidney), SALL1 (p.Phe447Tyr in patient with bilateral VUR) and RET genes (p.Gly533Ser in child with unilateral vesico-ureteric junction obstruction)." (PMID 34979951, 2022).
large-cell neuroendocrine pancreatic carcinoma (1 paper, 2024). "This case report describes the efficacy of selpercatinib, a selective RET inhibitor, in an unusual case of large-cell neuroendocrine pancreatic carcinoma (LCNEPAC) harboring a CCDC6::RET fusion." (PMID 39085487, 2024).
lichen (1 paper, 2024). "Moreover, prurit before the actual skin lesion might pinpoint a pathogenic contributor to lichen, other than the actual RET gene influence." (PMID 39337252, 2024).
malaria (1 paper, 2021). Malaria is a serious and sometimes fatal disease caused by a parasite that commonly infects a certain type of mosquito which feeds on humans. "Here, we show that Pv-RET triggers a decrease in ATP levels in peripheral blood, arguing that mitochondria are not preferentially generating ATP during malaria." (PMID 34311577, 2021). "Flavin adenosine dinucleotide (FAD) levels were lower in malaria patients even with no further addition of Pv-RET in the culture." (PMID 34311577, 2021).
mastocytosis (1 paper, 2017). A clonal myeloproliferative neoplasm characterized by the proliferation and accumulation of neoplastic mast cells in one or multiple organs or organ systems. "CEACAM1 knockdown upregulated cell growth of HMC1.2 cells harboring KIT mutations detected in clinical mastocytosis, whereas downregulated the growth of TT cells harboring RET mutations detected in clinical MTCs." (PMID 28332308, 2017). "As is the case for mastocytosis, CEACAM1 protein expression was observed in most MTCs and C cells with RET mutations, but not in C cells with normal RET." (PMID 28332308, 2017).
McCune-Albright syndrome (1 paper, 2020). McCune-Albright syndrome (MAS) is classically defined by the clinical triad of fibrous dysplasia of bone (FD), cafe-au-lait skin spots, and precocious puberty (PP). "Well-known examples of gain-of-function mutations with incomplete penetrance and tumor predisposition include RET mutations in multiple endocrine neoplasia (MEN) syndromes and GNAS1 mutations in McCune-Albright syndrome." (PMID 32235007, 2020).
metabolic syndrome (1 paper, 2024). A cluster of metabolic risk factors for CARDIOVASCULAR DISEASES and TYPE 2 DIABETES MELLITUS. "Higher levels of RET were associated with higher risk of the metabolic syndrome and a Mendelian randomisation in the same study suggested a causal relationship." (PMID 38374450, 2024).
multinodular goiter (1 paper, 2023). Nodular goiter characterized by more than one discrete tissue mass. "Results from qRT-PCR showed the absence of CCDC6::RET or NCOA4::RET rearrangements in normal tissues (n = 10) and benign (multinodular goiter, n = 10) cases." (PMID 37188126, 2023).
multiple myeloma (1 paper, 2021). "Previous studies showed that other RTK mutants, such as FGFR3K650E in multiple myeloma, RET multiple endocrine neoplasia type 2B (RETMEN2B), and PDGFRAY289C, are also tyrosine-phosphorylated via a secretory pathway." (PMID 34811450, 2021).
myoepithelial carcinoma (1 paper, 2025). "Specifically, the vandetanib therapy halted an actively progressing myoepithelial carcinoma with RET p.H926L, affording 35 months of continuous disease stabilization." (PMID 41373618, 2025). "In two patients with myoepithelial carcinoma, RET p.H926L and FGFR1 amplification warranted vandetanib and lenvatinib, respectively." (PMID 41373618, 2025).
myofibromatosis (1 paper, 2020). "MYH10-RET fusion, in particular, is, thus far, the most common RET lesion in spindle mesenchymal tumor and it was also identified in a case of infantile myofibromatosis." (PMID 32326537, 2020).